TNF (tumor necrosis factor)
Diseases named in the same sentence as TNF in open-access papers (continued):
Sharing a sentence is not in itself a finding about the gene and the disease.
osteoporosis (continued). "Choi indicated the enhancement of osteoblast function by glabridin (a constituent of liquorice), preventing osteoporosis and inflammatory bone diseases by reducing TNF-α-induced production of PGE2 and nitric oxide in osteoblasts." (PMID 39897257, 2025). "In obesity and T2DM, increased levels of pro-inflammatory cytokines like TNF-α and IL-6 lead to enhanced bone resorption and inhibit osteoblast differentiation, contributing to osteoporosis." (PMID 41007423, 2025). "In contrast, TNF-α was expressed in a similar proportion of patients with osteoporosis and normal body weight (63% vs. 60%), while only 10% of patients treated with HRT expressed TNF-α." (PMID 41141340, 2025). "TNF‐α influences the onset and progression of osteoporosis by inhibiting osteoblast differentiation through immunoinflammation." (PMID 40860907, 2025). "For example, elevated levels of pro-inflammatory cytokines like TNF-α in osteoporosis can enhance TRAF6 signaling, triggering the increased activity of NF-κB and PI3K/AKT pathways in osteoclasts, thereby promoting osteoclastogenesis and bone resorption." (PMID 40496246, 2025). "Our findings reveal that PGRN can effectively inhibit TNFα‐induced osteoporosis and has a certain osteogenic effect." (PMID 39910695, 2025). "The expression of inflammatory factors, such as interleukin-1 beta (IL-1β), IL-6, IL-17, and TNF-α, is markedly increased as osteoporosis progresses." (PMID 40873591, 2025). "In conclusion, quercetin improved in vitro models of osteoporosis and protected against TNF-α-induced impairment of osteogenesis in MSC." (PMID 41226117, 2025). "Osteoporosis involves chronic inflammatory responses where certain proinflammatory markers (e.g., tumor necrosis factor alpha, interleukin-1b, and interleukin-6) enhance osteoclast activity, reducing bone density." (PMID 41010472, 2025). "TNF-α antagonists have a delayed loss effect on BMD in patients, thereby reducing the incidence of osteoporosis and improving their quality of life." (PMID 39220949, 2024). "Studies have suggested that pro-inflammatory markers such as IL-6, IL-1, and TNF-alpha act as modulators of osteoblasts and osteoclasts, leading to up-regulation of osteoclast activation and osteoporosis." (PMID 38721534, 2024). "Five GMs, including GSTP1, TNF-α, TNF-β (LT-α), SLC6A14, and S1P, were associated with the musculoskeletal system and an increased risk of osteoporosis and reduced bone density." (PMID 40225935, 2024). "The inhibition of IL-1 or TNF-α has been demonstrated to prevent the onset of osteoporosis in ovariectomized mice." (PMID 39410150, 2024). "The expression of numerous inflammatory factors (IL-1β, IL-6, IL-17, and TNF-α) markedly increased during the progression of osteoporosis." (PMID 38895114, 2024). "DP exerts diverse medicinal properties, such as anti‐Alzheimer, anti‐inflammatory, hepato‐protection, anti‐osteoporosis, anti‐aging, and anti‐tumour effect via TNF‐α and NF‐κb pathway suppression." (PMID 38553831, 2024). "Therapeutic strategies targeting these inflammatory cytokines, such as the use of biologics that inhibit TNF-α or IL-1β, are being explored as potential interventions to modulate bone turnover in osteoporosis." (PMID 38656061, 2024). "In this context, the impact of TNF-α on bone health is especially pertinent to the development of bone diseases such as osteoporosis." (PMID 39200293, 2024). "Astragalus polysaccharides can reduce serum RANKL, osteocalcin, and TNF-α levels in OVX-induced osteoporosis mice and increase the content of osteoprotegerin (OPG) to prevent osteoporosis." (PMID 38606179, 2024). "To assess the diagnostic accuracy of hs-CRP, TNF-α, and IL-6 compared to the DXA standard method for osteoporosis, we employed the ROC curve." (PMID 39263180, 2024). "Under these conditions, an upregulation of pro-inflammatory cytokines such as Interleukin-1 (IL-1), IL-6, and tumor necrosis factor (TNF)-α has been observed, which are implicated in the osteoporosis process." (PMID 38675559, 2024).
osteoporosis (continued). "Age-associated increase in plasma TNFα and IL-10 has been associated with decreased bone mineral density and increased rates of osteoporosis; elevated plasma TNFα is now an established biomarker of frailty in older adults." (PMID 38560342, 2024). "In animal models, TNF-α induces osteoporosis by upregulating RANK expression and reducing OPG production, thereby promoting osteoclast differentiation." (PMID 38473934, 2024). "Chronically increased TNF-α levels increase the risks of inflammatory-related diseases like osteoporosis." (PMID 39457537, 2024). "Studies on osteoporosis in elderly individuals have further supported the role of TNF-α in systemic osteoporosis." (PMID 38473934, 2024). "Osteoporosis is a chronic inflammatory disease, in which pro-inflammatory cytokines including interleukin (IL)-1, tumor necrosis factor α (TNF-α), and IL-6 serve as primary mediators of the accelerated bone loss at estrogen deficiency." (PMID 37041523, 2023). "TNF-α plays an important role in the pathogenesis of osteoporosis and is a major inflammatory factor." (PMID 38081906, 2023). "In summary, our results indicated the in vitro regulating mechanism of quercetin on TNFα-impaired osteoporosis and in vivo treatment efficacy of quercetin on osteoporosis." (PMID 36983039, 2023). "The mean values of the serums of IL-1β, IL-6 and TNF-α in the osteoporosis group were significantly higher than those in the non-osteoporosis group (P < 0.05)." (PMID 37038178, 2023). "LPS stimulates NF-κB activation, followed by the release of inflammatory cytokines, including TNF-α and IL-1, which induce osteoclast differentiation and function, resulting in osteoporosis." (PMID 38003654, 2023). "Quercetin was found to upregulate Wnt/β-catenin while inhibiting NF-κB signaling activities, and thereby rescuing osteoporosis-induced tumor necrosis factor alpha (TNFα) impaired BMSCs osteogenesis." (PMID 36983039, 2023). "By inhibition of the Wnt pathway, these proteins along with several other cytokines, such as IL‐15, interferon gamma, IL‐17 MCP‐4 (monocyte chemoattractant protein), and TNF‐α blunt the bone formation there by leading to osteoporosis and its sequelae." (PMID 36911094, 2023). "Previous studies have provided support of an involvement of inflammatory cytokines, such as interleukin-6 and tumor necrosis factor, in the pathogenesis of osteoporosis." (PMID 37260443, 2023). "Deer antler polypeptides can treat inflammatory diseases and osteoporosis by inhibiting the release of TNF-α." (PMID 37373516, 2023). "In patients with end-stage renal disease, proinflammatory cytokines (IL-6 and TNF-α) are also attributed to osteoporosis." (PMID 37870853, 2023). "Tumor necrosis factor-α (TNF-α), not only the strongest bone resorption promoter but also bone formation inhibitor, is one of the most important factors for osteoporosis." (PMID 35358011, 2022). "Osteoporosis is mediated by a variety of inflammatory mediators, including TNF-α, RANKL, interleukin 1 beta, IL-6, and interferon gamma." (PMID 35187034, 2022). "For example, IL-1, IL-6, and TNF-α belong to the critical pro-inflammatory cytokines involved in osteoporosis and gout." (PMID 36615792, 2022). "MLN64-knockdown alleviates the severity of osteoporosis, down-regulates specific genes related to osteoclastogenesis including Runx2 and inflammatory factors such as TNF-α, IL-1β, IL-6, and MMP-1." (PMID 36387862, 2022). "TNF-α plays a critical role in the development of osteoporosis via regulating oxidative stress, bone homeostasis, and remodeling." (PMID 35154351, 2022).
osteoporosis (continued). "We also found that the serum level of IL-10 in the osteoporosis group was significantly lower than that in the control group and osteopenia group, while TNF-α was significantly higher in the osteoporosis group than that in the control group (p < 0.05)." (PMID 36032115, 2022). "Cluster analysis showed that osteoblasts-osteoclast in bone diseases were divided into five categories, including osteoblasts-osteoclasts expression, osteoporosis, multiple myeloma, tumor necrosis factor, and exosome." (PMID 35937845, 2022). "Bone resorption is predominantly induced by IL-6, IL-1β and TNF-α in osteoporosis, especially in the post-menopausal patients." (PMID 35381577, 2022). "Subsequent cellular studies confirmed that lncMIAT promoted the secretion of IL-6, TNF-α and IL-1β, which were important inflammatory cytokines for the disease progression of osteoporosis." (PMID 35381577, 2022). "Meanwhile, differences of IL-10 in osteopenia group versus osteoporosis group, and differences of TNF-α in control group versus osteopenia group were still significant." (PMID 36032115, 2022). "It is also necessary to investigate associations among inflammatory markers (IL-6, TNF-α, CRP), myosteatosis, blood lipid levels, adiposity, osteoporosis or osteopenia, bone demineralization and other comorbidities." (PMID 35330186, 2022). "After taking time after menopause, estrogen and BMI as covariates together, the differences of TNF-α in control group versus osteopenia group and control group versus osteoporosis group were significant." (PMID 36032115, 2022). "A number of inflammatory cytokines, most notably interleukin-6 (IL)-6, interleukin-1β (IL-1β), and tumor necrosis factor-α (TNF-α), were identified as major players in the pathogenesis of RA as well as RA-related comorbidities, such as osteoporosis." (PMID 36431340, 2022). "IL-6 and TNF-α are also pro-osteoclastic molecules that are markedly increased in patients with osteoporosis." (PMID 36615792, 2022). "After taking time after menopause, age, estrogen and BMI as covariates separately, the differences of IL-10 disappeared while the differences of TNF-α became significant between the control group and the osteoporosis group." (PMID 36032115, 2022). "In pathological condition in osteoporosis, pro-inflammatory cytokines such as tumor necrosis factor alpha (TNFα), IL1β, and IL17 were increased." (PMID 34115339, 2021). "Another possible mechanism involves inflammatory cytokines, in that osteoporosis patients have elevated systemic levels of pro-inflammatory cytokines IL-1, IL-6, and TNF-α." (PMID 33807030, 2021). "Osteoporosis in AS patients is mediated by pro-inflammatory cytokines, such as TNF alpha, Il-17, Il-1, which activate osteoclastogenesis by overexpressing the RANKL." (PMID 34830653, 2021). "Quercetin promotes bone marrow mesenchymal stem cells (BMSCs) proliferation and osteogenic differentiation, improves the in vitro model of osteoporosis, and provides protection against TNF-α-induced impairment of BMSC osteogenic function." (PMID 33880122, 2021). "In osteoporosis, estrogen deficiency leads to elevated levels of RANKL and inflammatory factors, including IL-6 and TNF-α." (PMID 34168561, 2021). "It has been found that increased expression of TNF-α can promote the formation of osteoporosis, and TNF-α expression is also affected by gut microbiota." (PMID 34336709, 2021). "Inflammatory cytokines, including tumor necrosis factor-α, interleukin-1β, and interleukin-6, have been postulated to be involved in AD, PD, and osteoporosis." (PMID 34955816, 2021). "To make clear the effects of ADSCs-Exos in osteoporosis, we attempt to culture TNF-α-treated primary osteoblasts with ADSCs-Exos." (PMID 34712334, 2021). "Regarding rheumatic diseases, PTX3 is involved in osteoblast proliferation in osteoporosis and its expression is induced by TNF-α in OA SF." (PMID 34208590, 2021).
osteoporosis (continued). "The specific cytokine that activates the process of osteoporosis is TNF-alpha, as it provokes the OPG-RANKL-RANK axis." (PMID 35103143, 2021). "In osteoporosis pathogenesis, tumor necrosis factor-α (TNF-α) is a proinflammatory cytokine which has been revealed to contribute to osteoporosis by regulating both osteoblasts and osteoclasts." (PMID 34712334, 2021). "OPG is a member of the tumor necrosis factor (TNF) receptor family implicated in the bone turnover process, osteoporosis, and premature vessel calcification." (PMID 34631895, 2021). "As IL-6 and TNF contribute to osteoclastogenesis, blockade of IL-6 and TNF can protect against osteoporosis in RA patients." (PMID 34681582, 2021). "LncRNA DANCR up-regulated in blood mononuclear cells promoted bone resorption through releasing TNF-α and IL-6 and finally resulted in osteoporosis." (PMID 35308164, 2021). "It has been reported that human peripheral-blood monocytes (PBMCs) from osteoporosis patients have 29–67% higher secretion of IL-1β, IL-6, and TNF-α in whole blood culture compared with healthy control subjects." (PMID 34917622, 2021). "TNF-α and IL-6 have been shown to mediate inflammation, which contributes to bone resorption and osteoporosis through stimulation of osteoclast development and activity." (PMID 32999682, 2020). "In the present study, a significant increase in serum NF-κB and TNF-α levels was observed in ovariectomized rats, which is an indicator of increased osteoclastic activity that accounts for osteoporosis." (PMID 33081068, 2020). "Many studies demonstrated that the level of inflammation factor tumor necrosis factor alpha (TNF-α) was obviously increased in postmenopausal women, which exerted important regulatory effects on bone turnover in estrogen deficiency-induced osteoporosis." (PMID 33425899, 2020). "Another potential target for treating osteoporosis is miR-146a, found in bone tissue, which can be induced by TNF-a/RANKL treatment, and has been found to inhibit osteoclastogenesis in mouse models." (PMID 32664424, 2020). "In vitro and in vivo studies have shown that the proinflammatory cytokines IL-6 and TNF-α are involved in the pathogenesis of osteoporosis and influence bone metabolism." (PMID 32963568, 2020). "In clinical settings, individuals with osteoporosis have been shown to have increased levels of serum TNF-α." (PMID 33007863, 2020). "Targeted by the miR-17-92 cluster, TNF-alpha expression was increased in the bone of elderly mice with osteoporosis, while the expression of miR-17/miR-20a-5p decreased." (PMID 32210807, 2020). "Age-dependent osteoporosis resulted in significant increase in serum levels of phosphate, bone specific alkaline phosphatase, hsCRP, IL-1β, IL-6, TNF-α, MDA, NO, and RANKL gene expression." (PMID 32532246, 2020). "Among them, TNF-α is a multifunctional cytokine that serves as a key regulator of osteoporosis pathology." (PMID 32400849, 2020). "Our results suggest that EXD exerted profound anti-osteoporosis effects, at least partially by reducing production of TNF-α and attenuating osteoblast apoptosis via Akt/Nrf2/HO-1 signaling pathway." (PMID 31551787, 2019). "We evaluated gene–gene and gene–physical activity interactions of the variants of tumor necrosis factor-α (TNF-α) and vitamin D receptor (VDR) genes on osteoporosis." (PMID 31887189, 2019). "We further explored these significant interactions by estimating the adjusted OR in osteoporosis according to TNF-α status for VDR genotype (minor–major/minor–minor and major–major genotypes)." (PMID 31887189, 2019). "One of the most important factors in osteoporosis is tumor necrosis factor-alpha (TNF-α), which is the strongest bone resorption enhancer and also inhibits bone formation." (PMID 31551787, 2019). "Quercetin improved bone structure and function in post-menopausal osteoporosis rats by suppressing the TNF-α-induced NF-κB/β-catenin pathway." (PMID 31826180, 2019).
osteoporosis (continued). "TNF-α is mainly produced by activated mononuclear macrophages and is closely related to osteoporosis, as high TNF-α expression can be detected in cases of osteoporosis." (PMID 32082385, 2019). "Overall, risperidone gave rise to osteoporosis by up-regulating TNF-α, and inhibiting collagen and BGP synthesis." (PMID 30810624, 2019). "Studies have shown a correlation between magnesium deficiency and osteoporosis, attributable to changes in parathyroid hormone (PTH), Vitamin D levels and increased pro-inflammatory cytokine secretion such as substance P, TNF-α, IL-1β, and RANKL." (PMID 32802092, 2019). "Many previous genetic studies explored the relationship of SNPs in VDR or TNF-α gene with osteoporosis." (PMID 31887189, 2019). "As biphasic factors, TNF-α and NF-κB are potential targets for novel drug design, and their suppressors can potentially be used to treat inflammatory bone diseases and osteoporosis." (PMID 29484117, 2018). "The mediators of osteoclastogenesis (and osteoporosis) include many other factors like hormones (viz. estrogen, parathormone) and inflammatory cytokines (e.g., TNF-α, PGE2, VEGF, etc.)." (PMID 29868029, 2018). "Nephrolithiasis has been demonstrated to accelerate bone loss; therefore, osteoporosis could be possibly attributed to either the presence of hypercalciuria or decreased dietary calcium intake, and elevated serum levels of inflammatory factors such as IL-1, IL-6 and TNF-α." (PMID 29996796, 2018). "Combined UC-MSC and TNF-α set will help to further clarify the mechanism of UC-MSC on osteoporosis in CIA." (PMID 29853911, 2018). "In fact, several in vitro and rodent studies have revealed that proinflammatory cytokines such as interleukin-6 (IL-6), interleukin-1 (IL-1), and tumor necrosis factor-alpha (TNF-α) are involved in the pathogenesis of osteoporosis." (PMID 29996796, 2018). "Nigella sativa supplementation reverses osteoporosis in ovariectomized rats in part by reduction of TNF-alpha and MDA (Seif AA, 2014 ▶)." (PMID 27247920, 2016). "MiR-3077-5p, a miRNA upregulated by TNFα in MSCs from osteoporosis bone marrow of mice, was demonstrated to directly target Runx2 and to inhibit Runx2 translation." (PMID 26877865, 2016). "High NO level contributes to the pathogenesis of osteoporosis by enhancing the ability of IL-1 and TNF to stimulate osteoclast activity." (PMID 25195641, 2014). "Osteoporosis studies showed that strontium compounds inhibit apoptosis of osteoblasts by reducing the expression of TNF-α and inflammatory cytokines." (PMID 27355060, 2014). "Activation of NF-κB plays an important role in the pathogenesis of osteoporosis by the upregulation of TNF-α, IL-1β, ICAM-1, iNOS, and COX-2 expressions." (PMID 24348690, 2013). "A blocking antibody to TNFα abrogated this increased osteoclastogenesis, suggesting that osteoporosis in the TSHR−/− mice was TNFα mediated." (PMID 23818914, 2013). "The expressions of TNF-α and IL-1β were found to be enhanced in both animal model and patients with osteoporosis." (PMID 24348690, 2013). "Calcitriol (1,25(OH)2D3) supplementation for 6 months in post-menopausal women with osteoporosis resulted in a significant reduction in serum TNF-α concentrations and an increase in bone mineral density." (PMID 18652680, 2008). "Notably, unlike adefovir, tenofovir additionally contributes to the development of osteoporosis by affecting inflammatory cytokine pathways such as IL-17, IL-1β, and TNF." (PMID 40687725, 2025). "Thus, by altering the RANKL/OPG ratio, TNF-α enhances bone resorption, contributing to osteoporosis progression." (PMID 40873591, 2025). "Similarly, infliximab alleviated AD-like pathology by modulating the TNF-α/Wnt/β-catenin signaling pathway and improved osteoporosis and tendon inflammation in RA patients." (PMID 40153574, 2025). "Since TNFα affects the balance of bone metabolism, suppression of TNFα‐induced inflammatory osteoporosis may be a potential target for the treatment of osteoporosis." (PMID 39910695, 2025).